Y_RNA (Y RNA )
Gene: Miscellaneous RNA gene on chromosome 1 (211,803,017 to 211,803,104, forward strand). Ensembl gene ENSG00000212205.
Homologues: Orthologues: chimpanzee Y_RNA (99% identical). Paralogues in human: RNY1P8 (77% identical), Y_RNA (77% identical), RNY1P11 (76% identical), RNY1P5 (76% identical), Y_RNA (76% identical), RNY1 (75% identical), RNY1P7 (75% identical), Y_RNA (75% identical), Y_RNA (74% identical), RNY1P16 (73% identical), Y_RNA (73% identical), RNY1P1 (72% identical), and 83 more.